NOTCH1 (notch receptor 1)
Diseases named in the same sentence as NOTCH1 in open-access papers (continued):
Sharing a sentence is not in itself a finding about the gene and the disease.
intracerebral hemorrhage (4 papers, 2016 to 2021). A cerebrovascular disorder characterized by bleeding into one or both cerebral hemispheres including the basal ganglia and the cerebral cortex. "It has been demonstrated that Notch-1 signaling is a critical regulator of intracerebral hemorrhage (ICH)-induced reactive astrogliosis." (PMID 33971906, 2021). "Notch1 maturation participates in apoptosis and inflammation following intracerebral hemorrhage (ICH)." (PMID 29221132, 2017). "A later study in a rat model of intracerebral hemorrhage, in which the specific inhibitor of the y-secretase enzyme DAPT was used, showed that Notch1 signaling was upregulated." (PMID 34222228, 2021).
invasive breast carcinoma (4 papers, 2011 to 2020). A carcinoma that infiltrates the breast parenchyma. "In a malignant environment, such as invasive breast carcinoma, cleaved (activated) Notch1 has been observed in a subset of lymphatic endothelial nuclei, indicating that Notch1 is not only expressed but is activated in tumor lymphatic vessels." (PMID 21939555, 2011). "Actually, deregulation of miR‐204, miR‐200c, miR‐34a, and miR‐10b simultaneously could significantly reduce the survival rate of breast invasive carcinoma via up‐regulation of OCT4, SOX2, KLF4, c‐MYC, NOTCH1, SNAI1, ZEB1, and CDH2 and down‐regulation of CDH1." (PMID 30710426, 2019).
laryngeal squamous cell carcinoma (4 papers, 2017 to 2025). A squamous cell carcinoma that arises from the larynx. "Notch1 and Ki-67 expression in laryngeal squamous cell carcinoma (LSCC) tissues was detected by immunohistochemistry." (PMID 35982489, 2022). "Notch1 knockdown in a laryngeal squamous cell carcinoma cell led to reduced Cyclin D1 and Cyclin E expression." (PMID 28860516, 2017).
leukoplakia (4 papers, 2015 to 2024). A white patch or plaque on a mucous membrane that cannot be characterized clinically or pathologically as any other disease. "Additionally, almost 60% of leukoplakia patients with mutated NOTCH1 carried mutations that were also identified in OSCC, indicating an important role of these clonal events in the progression of early neoplasms." (PMID 26262956, 2015).
liposarcoma (4 papers, 2016 to 2026). A usually painless malignant tumor that arises from adipose tissue. "The full method detailed below can be applied to determine the effects of muscle-specific Notch1 activation in the mdx mouse model and to analyze previously published microarray data of human liposarcoma cell lines." (PMID 30547052, 2018).
liver disease (4 papers, 2018 to 2025). "Moreover, roles of Piezo1 and Notch1 in chemotactic chemokine release, portal hypertension and liver fibrogenesis were recently suggested and will be interesting to investigate further in regard to shear stress activation of Piezo1-ADAM10/Notch1 signalling." (PMID 32484440, 2020). "Jagged1 deficiency might also affect the transient increase in Notch1 and in the active Notch1 intracellular domain (N1ICD) necessary to induce the TGF-β1-rich primary SASP, TGF-β being an important promotor of the paracrine transmission of senescence in liver disease." (PMID 37099537, 2023).
liver inflammation (4 papers, 2020 to 2023). "Our findings demonstrate the unexpected role of myeloid Notch1 signaling-induced Snail activation in negatively modulating the NLRP3-mediated innate immune response during IR-triggered liver inflammation." (PMID 31673056, 2020). "In contrast, the adoptive transfer of HSF1-expressing macrophages to myeloid-specific Notch1 knockout mice promoted Snail activation and alleviated IR-triggered liver inflammation, which suggests that the Notch1/HSF1/Snail axis is a therapeutic target for liver inflammatory injury." (PMID 34239690, 2021). "In this study, we revealed that disruption of macrophage Notch1 activated the TAK1-mediated inflammatory responses and RIPK3-mediated hepatocyte necroptosis through activation of β-catenin in IR stress-induced liver inflammation." (PMID 36114543, 2022). "Our results highlight the importance of JAG1-mediated myeloid Notch1/HSF1/Snail signaling as a key regulator of NLRP3 activation and cell apoptosis during IR stress-mediated liver inflammation." (PMID 31673056, 2020). "We demonstrate that myeloid Notch1 signaling promotes heat shock transcription factor 1 (HSF1) and Snail activation, which in turn controls NLRP3-mediated innate immunity during IR-triggered liver inflammation." (PMID 31673056, 2020). "In our previous study, we discovered that Notch1 signaling controls the HMGB1/TLR4/NF-κB axis in AILI to regulate NLRP3 inflammasome activation, illuminating the critical function of the Notch1-Hes1 signaling cascade response in regulating innate immunity in APAP-triggered liver inflammation." (PMID 37370115, 2023).
lung diseases (4 papers, 2019 to 2023). "The NRs, Notch1, and 2 are critical in various lung diseases, hence we surveyed their expression on phagocytes as well." (PMID 35603470, 2022). "The investigated focused on the participation of miR-34a in COPD-TS and other pulmonary diseases resulting in the Notch1 protein." (PMID 31775690, 2019).
myeloid neoplasm (4 papers, 2016 to 2025). Proliferation of myeloid cells originating from a primitive stem cell. "It has been reported that PHF6 and NOTCH1 mutations were often implicated in the development of T-ALL and less frequently in AML and other myeloid neoplasms." (PMID 41341582, 2025).
prostate tumor (4 papers, 2015 to 2021). "Using prostate conditional inactivation of both Pten and Notch1 along with preclinical trials carried out in Pten-null prostate conditional mouse models, we demonstrate that Pten-deficient prostate tumours are addicted to the NOTCH signalling." (PMID 27941799, 2016). "The enhanced γ-secretase activity in Ptenpc−/− tumours and their dependence on Notch1 signalling suggested that Pten-deficient prostate tumours could be highly responsive to the treatment with GSIs." (PMID 27941799, 2016). "In summary, our current investigation reveals that MSCs, an important mediator in the prostate tumor environment, contributed to the stemness of PCa cells when directly in contact with MSCs via activation of the Jagged1/Notch1 pathway." (PMID 34001269, 2021). "Tumor suppressor p21WAF1/CIP1 contributes to the overrepresentation of “regulation of progression through the cell cycle in prostatic neoplasms” within the list of genes up-regulated by Notch1." (PMID 27384993, 2016). "Prostate was the most frequently mutated cell type for both NOTCH1 and NOTCH2 but prostate tumor cell lines did not contain any mutations in NOTCH3 or NOTCH4 (right hand side)." (PMID 25907971, 2015).
subarachnoid hemorrhage (4 papers, 2019 to 2024). A serious neurological disorder characterized by intracranial hemorrhage into the subarachnoid space. "Furthermore, studies on mesenchymal stem cells (MSCs) have revealed their role in mitigating early brain injury following subarachnoid hemorrhage (SAH) by suppressing Notch1‐dependent neuroinflammation." (PMID 39607309, 2024). "Fluoxetine may ameliorate early brain injury after subarachnoid hemorrhage through anti-apoptotic effects and Notch1/ASK1/p38 MAPK signaling pathway." (PMID 35383529, 2022). "This investigation provides a novel finding that Fluoxetine may ameliorate early brain injury after subarachnoid hemorrhage through anti-apoptotic effects and Notch1/ASK1/p38 MAPK signaling pathway." (PMID 35383529, 2022).
T cell neoplasms (4 papers, 2009 to 2024). "The molecular basis underlying precursor T-cell neoplasms are highly heterogeneous and may involve deregulation of multiple signaling pathways such as NOTCH1, JAK/STAT, PI3K/AKT, MAPK/ERK, c-MYC or mTOR8–10." (PMID 39033228, 2024). "Next, Notch-1 attracted attention because alteration of Notch-1 was posited to play a role in the pathogenesis of several T cell neoplasms." (PMID 36017236, 2022). "However, three samples expressed neither Notch1 and/or Jagged1 and none of the mature T-cell neoplasm samples expressed either protein." (PMID 23181106, 2012).
temporal lobe epilepsy (4 papers, 2017 to 2024). A localization-related (focal) form of epilepsy characterized by recurrent seizures that arise from foci within the temporal lobe, most commonly from its mesial aspect. "A recent study indicated that the silencing of miRNA-146a decreases oxidative stress and the inflammatory response in a rat model of temporal lobe epilepsy (TLE); one of the genes involved in the process was Notch1." (PMID 35052815, 2022). "Microglial activation and phenotypic switching play a critical role in neurological disease, and in temporal lobe epilepsy (TLE) mouse model and in BV2 cells, RUNX1 may play a critical role in microglial phenotype through the Notch1 signaling pathway." (PMID 38385040, 2024). "In human temporal lobe epilepsy, patients with hippocampal sclerosis have higher NOTCH1 expression than patients without hippocampal sclerosis." (PMID 28273100, 2017).
thymoma (4 papers, 2022 to 2026). A neoplasm arising from the epithelial cells of the thymus. "These molecules were not detectable in the EL4 thymoma cell line, which is known to express low levels of NOTCH1." (PMID 36765626, 2023).
Alagille syndrome (3 papers, 2014 to 2019). "NOTCH signaling is implicated in Alagille syndrome which has a high rate of VUR, and we identified CNVs in NOTCH1." (PMID 31404082, 2019). "Autosomal dominant mutations in NOTCH1 cause the Adams–Oliver syndrome (OMIM 616028), while autosomal dominant mutations in NOTCH2 are reported in the Alagille syndrome 2 (OMIM 610205) and in the Hajdu–Cheney syndrome (OMIM 102500)." (PMID 31555317, 2019).
allergic asthma (3 papers, 2014 to 2020). A asthma with a basis in a pathological type I hypersensitivity reaction. "The anti-inflammatory activities of curcuminoids in several studies have shown that curcumin was able to regulate receptor levels of Notch1/2 and GATA3 in acute allergic asthma caused by inflammation in BALB/c mice." (PMID 33322573, 2020). "Notch1 was activated in both mouse and human in vitro-polarized Th17 cells, and blockade of Notch signaling in vivo down-regulated Th17 differentiation, resulting in reduction in Th17-mediated disease progression in EAE, collagen-induced arthritis, and allergic asthma mouse models." (PMID 30988066, 2019).
ameloblastoma (3 papers, 2020 to 2024). The most common odontogenic tumor, arising from the epithelial component of the embryonic tooth and usually affecting the molar-ramus region of the mandible or maxilla. "Here, we showed that NOTCH2 and NOTCH3, but not NOTCH1 (data not shown), are expressed at the interface between the ameloblastoma epithelium and the underlying stroma, which is a location pivotal for the acquisition of an invasive phenotype." (PMID 32155948, 2020). "Some studies have reported the expression of NOTCH1, 2, and 3, as well as their ligands DLL1, DLL4, and JAG1, in all ameloblastomas analyzed." (PMID 32155948, 2020). "As shown in ameloblastoma, transcription and post-transcription factors such as hypoxia-inducible factor 1α (HIF-1α), ADAM-12, and NOTCH1 are directly involved in an HB-EGF autocrine amplification loop and facilitate local tumor invasiveness." (PMID 31936715, 2020).
angiosarcoma (3 papers, 2013 to 2025). A malignant tumor arising from the endothelial cells of the blood vessels. "NOTCH1 specifically has been linked to cutaneous angiosarcomas, while NOTCH2 has been associated with visceral angiosarcomas with poorer survival than NOTCH1." (PMID 41301029, 2025). "ATRX loss and reduced expression of Notch1 and Notch2 have also been documented in angiosarcomas." (PMID 38826780, 2024). "We identified mutations in both NOTCH1 (n = 19, 5.29%) and NOTCH2 (n = 19, 5.29%) in the database, consistent with prior findings of mutations in both human and animal forms of angiosarcoma." (PMID 41301029, 2025). "Activation of NOTCH1 was also detected in a majority of angiosarcomas, in line with the observation that NICD1 is readily detectable in normal endothelial cells within tumor stroma." (PMID 23825651, 2013). "Moreover, studies suggest a suppressive role for Notch1 in liver endothelial cell function, potentially contributing to hepatic angiosarcoma development." (PMID 38826780, 2024). "However, we observed ongoing NOTCH1 activation in a high fraction of human angiosarcomas, particularly in those that are well differentiated." (PMID 23825651, 2013). "Thus, while loss of NOTCH1 function may be associated with progression of angiosarcoma, it may not be essential for its genesis." (PMID 23825651, 2013). "An initial screen of 3 well-differentiated angiosarcomas of the scalp revealed diffuse NICD1 positivity in all 3 tumors, prompting us to study NOTCH1 activation in an arrayed collection of 54 additional angiosarcomas." (PMID 23825651, 2013).
bone metastasis (3 papers, 2015 to 2025). Transfer of a neoplasm from its primary site to bones. "NOTCH1 mutations were linked to disease‐free, distant metastasis‐free, bone metastasis‐free, progression‐free, and overall survival in samples of 49–125 cases." (PMID 40789681, 2025). "In this study, only Notch-1 expression was found to be statistically significantly higher in bone metastasis tissues compared to primary PC." (PMID 26146569, 2015). "Finally, multivariate analysis including the panel of five CTC-biomarkers in combination with the presence of bone metastasis resulted in GAPDH, NOTCH1 and PTP4A3 as independent predictors of PFS; GAPDH and ITGB3 showed predictive value for OS." (PMID 27901069, 2016).
breast adenocarcinoma (3 papers, 2013 to 2021). "We found that ectopic expression of the Notch1 intracellular domain (N1ICD) in MCF-7 breast adenocarcinoma cell line caused reduction and delocalization of E-CADHERIN levels and increased migratory and invasive abilities." (PMID 23826634, 2013).
carcinoma in situ (3 papers, 2015 to 2023). "Notch1 was positively related to progression, exhibiting elevated expression in invasive ductal cancer (IDC) relative to carcinoma in situ(pooled OR = 3.75, 95%CI: 1.8–7.78, p = 0.981 and I2 = 0.0%)." (PMID 26121683, 2015).
cerebral infarction (3 papers, 2020 to 2022). An ischemic condition of the brain, producing a persistent focal neurological deficit in the area of distribution of the cerebral arteries. "It is also found that osthole (25, 50, and 100 mg/kg) could impede cerebral infarction, hippocampus neuronal lesion, and apoptosis created by middle cerebral artery occlusion/reperfusion (MCAO/R) model via initiating Notch 1 signaling pathway in a dose-dependent manner in vivo." (PMID 32028721, 2020).
chondrosarcoma (3 papers, 2015 to 2022). A malignant cartilaginous matrix-producing mesenchymal neoplasm arising from the bone and soft tissue. "More importantly, SOX9 had been proven to participate in Notch 1 induced cell motility, cell invastion and loss of E-cadherin, and Notch signaling pathway was found participate in cellular differentiation and proliferation in chondrosarcoma." (PMID 26317788, 2015).
chronic myelomonocytic leukemia (3 papers, 2016 to 2020). A myelodysplastic/myeloproliferative neoplasm which is characterized by persistent monocytosis, absence of a Philadelphia chromosome and BCR/ABL fusion gene, fewer than 20 percent blasts in the bone marrow and blood, myelodysplasia, and absence of PDGFRA or PDGFRB rearrangement. "NOTCH-1 mutations have also been described in patients with chronic myelomonocytic leukemia (CMML)." (PMID 32711424, 2020).
colorectal adenoma (3 papers, 2013 to 2020). An adenoma that arises from the colon or rectum. "We investigated mRNA expression of four Notch receptors (Notch1–4), five ligands (Jag1, Jag2, Dll1, Dll3, and Dll4), and four target genes (Hes1, Hes5, Hey1, and Hey2) using highly specific TaqMan gene expression assays in colorectal adenomas and cancers." (PMID 32211044, 2020).
Crohn disease (3 papers, 2017 to 2020). A gastrointestinal disorder characterized by chronic inflammation involving all layers of the intestinal wall, noncaseating granulomas affecting the intestinal wall and regional lymph nodes, and transmural fibrosis. "We employed Mycobacterium avium paratuberculosis (MAP) infection in Crohn’s disease (CD) as a model to demonstrate the role of Notch-1/IL-6 signaling on MCL-1 based apoptosis and intracellular MAP infection and persistence." (PMID 33072191, 2020).
diabetic neuropathy (3 papers, 2017 to 2022). A chronic, pathological complication associated with diabetes mellitus, where nerve damages are incurred due to diabetic microvascular injury involving small blood vessels that supply these nerves, resulting in peripheral and/or autonomic nerve dysfunction. "Intrathecal injection of either Notch1 inhibitor DAPT or TLR4 inhibitor TAK ameliorated diabetic neuropathic pain behaviors, which implied that inhibition of either Notch1 signaling or TLR4 signaling alleviated painful diabetic neuropathy." (PMID 29097792, 2017). "The fact that Notch signaling pathway is crucial for neuronal differentiation and survival suggested that interactions between TLR4 with members of Notch1 signaling regulate certain aspects of latency of the neurons affected diabetic neuropathy." (PMID 29097792, 2017). "In this study, the pain behaviors developed in the painful diabetic neuropathy model were reversed by either Notch1 inhibitor DAPT or TLR4 inhibitor TAK, suggested that different pathways were involved." (PMID 29097792, 2017). "Summing up, in light of the interactions of Notch1 and TLR4 signaling pathways, both Notch1 and TLR4 signaling pathway may indeed play a significant role in development of neuropathy, which could be linked to the nociceptive behavior in diabetic neuropathy." (PMID 29097792, 2017). "Further, the Notch signalling pathway has been studied in diabetic retinopathy, and crosstalk between the Notch-1 and TLR4 signalling pathways has been reported to be one of the key mechanisms in the development and/or progression of diabetic neuropathy." (PMID 35291879, 2022). "Another work, on the other hand, showed Notch1 signaling promoted TNF-α production in neurons of diabetic neuropathic rats, as an essential mechanism in diabetic neuropathy." (PMID 34646085, 2021). "In the present study, both DAPT and TAK were used as the specific inhibitors for detecting the interactions of Notch1 and TLR4 in the progression of diabetic neuropathy." (PMID 29097792, 2017). "PCR and Western blot analysis revealed time-dependent upregulation of TLR4 mRNA and protein, Notch1 mRNA, NICD1 protein, which was paralleled by pain behavior of the established diabetic neuropathy." (PMID 29097792, 2017). "Interestingly, interactions of Notch1 and TLR4 signaling pathway play an essential role in DRG of the diabetic neuropathy model because inhibition of one pathway could affect the activation of the other." (PMID 29097792, 2017). "Notch1 inhibition may or may not have direct influence on the inhibitory effect of the inflammation induced by diabetic neuropathy, but might be due to the decreased activity of neurons related to the pain behaviors by regulating the fate of these cells." (PMID 29097792, 2017).